PTH (parathyroid hormone)
Diseases named in the same sentence as PTH in open-access papers (continued):
Sharing a sentence is not in itself a finding about the gene and the disease.
cancer (continued). "PTH receptor activation influences cancer progression in vitro, yet the effect of elevated PTH on pediatric cancer survival is unexamined." (PMID 39141058, 2024). "This study identifies elevated parathyroid hormone as a potential marker for poor outcomes in patients with pediatric cancer, emphasizing the need for adequate vitamin D and calcium management." (PMID 39141058, 2024). "Historically, a connection between PTH and cancer has been described when PTH-related peptide (PTHrP) was identified in 1988 by three groups as the hormone responsible for humoral hypercalcemia in cancer." (PMID 39141058, 2024). "Parathyroid hormone (PTH) has emerged as a promising biomarker because of its involvement in calcium metabolism and cancer progression." (PMID 39816276, 2024). "The metabolic pathways of significance that were regulated included mineral absorption, ascorbate and aldarate metabolism, cholesterol metabolism, choline metabolism in cancer, parathyroid hormone synthesis, secretion and action, and oxidative phosphorylation." (PMID 39594072, 2024). "Laboratory data from 4,349 patients (0–18 years) at a tertiary pediatric cancer unit were analyzed for the highest PTH and lowest 25OHD levels at diagnosis and the following 5 years." (PMID 39141058, 2024). "Increased Ca levels in the body can reduce the release of parathyroid hormone, which was thought to play a promoting role in the development of cancer." (PMID 36937365, 2023). "Together, these findings support further experimentation with PTH for treating MRONJ in non-cancer patients." (PMID 37404809, 2023). "PTHrP is produced by cancer cells and mimics the effects of parathyroid hormone (PTH) to elevate serum calcium concentrations." (PMID 37767367, 2023). "Regarding the pathway analysis of downregulated miRNAs, the top three significantly downregulated pathways were the Rap1 signalling pathway, proteoglycans in cancer, and the pathway of parathyroid hormone synthesis, secretion and action." (PMID 36621805, 2023). "KEGG analysis showed that a large number of these genes were enriched in the synthesis and secretion of parathyroid hormone, and were significantly enriched in the transcriptional regulation of cancer." (PMID 36941602, 2023). "There was a higher incidence of low POD1 PTH levels among patients undergoing total (versus completion) thyroidectomy, central neck dissection, having cancer diagnosis, and with parathyroid tissue identified on surgical pathology." (PMID 35247092, 2022). "Indeed, the AUCs of miRNA‐342‐3p, serum calcium and PTH levels are equivalent; in the same time, the combination of them appears to be the most promising preoperative models to distinguish the PC from the PA in individuals with increased risk of malignant tumour." (PMID 34505413, 2021). "PTH and PTHrP, which signal through the same receptor Pth1r, induce adipose tissue and muscle wasting in murine models of cancer and CKD31,33." (PMID 34302016, 2021). "Increased serum PTH concentrations were associated with accelerated WAT browning and muscle wasting in mouse models of CKD and cancer." (PMID 34943890, 2021). "SERM ranks best in reducing risk of cancer and CVD; however, it causes high incidence of death (PTH (77.3%) > SERM (72.4%) > placebo (47.2%) > BP (37.6%) > mAb (15.5%)) among the available interventions evaluated." (PMID 34300210, 2021). "These five patients manifested high levels of serum PTH, calcium, and BTMs, and were suspected of carcinoma by ultrasound or sestamibi preoperatively." (PMID 33716964, 2021). "In our study, PTH values were markedly higher than 10 times the normal range, and hypercalcemic crisis accounted for 38.5% of the carcinoma cases." (PMID 33716964, 2021). "The repurposing of PTH anti-psychotics for cancer therapy has been proposed, even though their cellular targets have not been identified, as they were generally assumed to work largely through inhibition of dopamine receptors." (PMID 32905878, 2020).
cancer (continued). "When analyzing the PC group exclusively, we found that SST5C-negative carcinomas appeared to have higher calcium and PTH levels than the entire PC group average." (PMID 31336364, 2019). "Since the CXCR4/CXCL12 axis has been established to play an important role in the homing of cancer cells to the bone, the effect of PTH inhibition of CXCL12 secretion by MC3T3-E1 cells (preosteoblasts) was confirmed." (PMID 30151009, 2018). "It has also been demonstrated that some cancers express PTH/PTHrp and are related to mitogenic signals." (PMID 30581552, 2018). "These include calcitonin (the clinical investigation of which in cancer patients has been very limited) and teriparatide, a recombinant human PTH analogue." (PMID 29353450, 2018). "La morbidité et la mortalité lors du cancer parathyroïdien sont essentiellement liées à l'hypersécrétion de PTH et à l'hypercalcémie qui en résulte, plutôt qu'à l'extension tumorale elle-même." (PMID 28819506, 2017). "Age, serum PTH, self-reported cancer, early menopause and use of calcium were negatively associated with forearm BMD in the same group." (PMID 28253304, 2017). "Reflecting the pleiotropic functions of the vitamin D/PTH axis, other potential candidate genes were also implicated immune/inflammatory processes (NKX2, PSMA6, SNX6) as well as cancer (NKX2, NKX3, PAX9)." (PMID 27579147, 2016). "Our results are in agreement with findings from epidemiological studies showing that PTH correlates with cardiovascular and even cancer mortality." (PMID 24782595, 2014). "Given that inflammation is involved in the pathophysiology of cardiovascular disease, cancer, aging, and other conditions, our results provide clues on which to base further investigations of the mechanistic aspects of the PTH-inflammatory link." (PMID 24782595, 2014). "In conclusion, this study presents GC90/IRIV as a good vaccine candidate to be investigated in clinical trials for human cancers and bone metastases overexpressing PTH-rP." (PMID 12838324, 2003). "In PM-M8, two hormones with their full concentration ranges induced a significantly higher energy production in control cells: parathyroid hormone (B1–B6) and Arg8-vasopressin (A7–A11), with the exception of A12, which significantly increased energy production in cancer cells." (PMID 41590662, 2026). "Furthermore, compared with the reference group, patients with cancer-type APTs were significantly younger and had significantly higher levels of corrected calcium and PTH." (PMID 40434298, 2025). "However, one patient with a cancer-type APT exhibited persistently high PTH levels after parathyroidectomy." (PMID 40434298, 2025). "Parathyroid hormone is a novel mediator of cachexia in experimental CKD or cancer." (PMID 41262737, 2025). "Thus, routine monitoring of calcium (and PTH/PTHrP) in cancer patients helps detect metabolic derangements early and guides interventions (hydration, bisphosphonates, etc.)to mitigate complications." (PMID 41367907, 2025). "The authors noted a significant correlation between serum beta-hCG and PTH in the carcinoma cohort (r = 0.786, p < 0.05) and documented a significantly higher median serum beta-hCG in the carcinoma cohort compared to both the primary and secondary hyperparathyroidism cohorts." (PMID 40530390, 2025). "However, lower preoperative PTH and calcium levels have been associated with a higher incidence of PTC and asymptomatic patients have been described with more aggressive carcinoma, which further challenges this theory." (PMID 40255724, 2025). "Additionally, ectopic PTH secretion by NETs or carcinomas leads to severe HPT, which has been noted in sporadic case reports." (PMID 41561737, 2025). "The reported association of high PTH with lower EFS in some cancers was noted in the absence of a temporal relationship." (PMID 39141058, 2024).
cancer (continued). "The explanation for this may be that children with cancer in that study were under cancer treatment which may have influenced the metabolism of PTH." (PMID 38523666, 2024). "Cancer patients had higher average levels of parathyroid hormone (PTH), with a mean of 399 pg/mL." (PMID 39712803, 2024). "Given the hypothesis that elevated PTH levels may impact EFS and OS in patients with cancer, the analysis was focused on the highest PTH level recorded for each patient during the 5-year period from diagnosis." (PMID 39141058, 2024). "The top 10 significant KEGG pathways and their functional classification by 5 main categories include bacterial invasion of epithelial cells; Fc gamma R‐mediated phagocytosis; choline metabolism in cancer; parathyroid hormone synthesis, secretion and action; and Sphingolipid signaling pathway." (PMID 39617640, 2024). "Of particular note, the pathways of cholesterol metabolism, mineral absorption, ascorbate and aldarate metabolism, choline metabolism in cancer, parathyroid hormone synthesis, secretion and action, and oxidative phosphorylation were identified as vital metabolic pathways (p < 0.05)." (PMID 39594072, 2024). "However, it is important to remember that PTH is contraindicated in patients with cancer because it increases bone remodeling, possibly contributing to bone metastasis." (PMID 37404809, 2023). "Patients with a CAR ≥ 0.5 were older (p < 0.001), were more frequently Caucasian (p = 0.005), had more frequently cardiovascular disease (p < 0.001) and cancer (p < 0.001), had lower hemoglobin (p < 0.001), lower PTH (p = 0.036), and higher ferritin levels (p = 0.007)." (PMID 36995004, 2023). "Differential diagnosis from parathyroid hyperplasia and adenomas could be complex, but the suspicion of cancer increases in cases of certain findings, such as higher levels of serum PTH and calcium, parathyrotoxicosis, and a palpable neck mass." (PMID 38027123, 2023). "In CKD and cancer, PTH and tumor-derived PTHrP drive adipose tissue browning and cachexia." (PMID 37509715, 2023). "Current clinically available therapeutic agents for inflammatory osteolysis like estrogen, bisphosphonates, and parathyroid hormone are effective, but still have some limitations and side effects including increased cancer risks, aseptic jaw osteonecrosis, and atypical femur fracture." (PMID 36249770, 2022). "The shared DEGs in the liver at 12 h and 48 h postinjection of poly (I:C) could be enriched in: steroid biosynthesis; parathyroid hormone synthesis, secretion and action; microRNAs in cancer; metabolic pathways." (PMID 36077207, 2022). "Differentially expressed genes in aortic VSMCs between HS and ARC and HS and T16 groups were significantly enriched in parathyroid hormone synthesis, secretion, and action: MicroRNAs in cancer and proteoglycans in cancer and MicroRNAs in cancer and ECM–receptor interaction." (PMID 36359280, 2022). "In addition, genes were highly enriched in MAPK signalling pathway, proteoglycans in cancer, parathyroid hormone synthesis, secretion and action by KEGG analysis." (PMID 32233022, 2020). "The results may also have implications for the use of PTH as a bone anabolic agent in the cancer setting and highlights the need to define the specific role(s) of osteoblasts in the development of bone metastasis in human disease." (PMID 30261597, 2018). "MEK/ERK has been proposed as a crucial regulator of cell fate choices based on its differential activation kinetics to transient vs. sustained stimuli in fibroblasts, neural and carcinoma cells and to intermittent vs. continuous PTH in PTH-responsive kidney cells." (PMID 30576321, 2018). "In women (N = 1,792), inclusion of age, height, BMI, serum PTH, serum creatinine, serum calcium, self-reported cancer, early menopause and use of vitamin D, calcium and estrogen from S2 Table resulted in the same negative trend across the rs4870044 genotypes, with P = 0.084." (PMID 28253304, 2017).
cancer (continued). "The early identification of cancer and appropriate resection of the affected glands quickly permitted the metabolic control, as noted in the assessment of serum levels of inorganic phosphorus and PTH after the surgery." (PMID 26881146, 2016). "Further clinical and observational studies exploring the potential roles of calcium and phosphate in cancer should take into account their regulators such as vitamin D, parathyroid hormone, and fibroblast growth factor 23 (FGF-23) in order to fully comprehend how they are involved in carcinogenesis." (PMID 26284119, 2015). "Since calcium homeostasis is mainly influenced by vitamin D and parathyroid hormone instead of dietary calcium, the use of serum calcium could be useful in investigating the aetiology of cancer." (PMID 26284119, 2015). "Although extremely high PTH and calcium level (>3.5 mmol/L) may be the first indication of malignancy, a wide overlap between benign and malignant tumors has been reported." (PMID 23566353, 2013). "Since calcium homeostasis is mainly influenced by vitamin D and parathyroid hormone (PTH) instead of dietary calcium, the use of serum calcium may enable further insight into the relation between calcium metabolism and cancer risk." (PMID 23866097, 2013). "E. Shane suggested that benign disease have PTH level <2 times the upper limit of normal, whereas carcinoma may have PTH level up to 10 times the upper limit of normal." (PMID 22840059, 2012). "Examination of infectious disease death rates and cancer rates can be correlated to PTH level." (PMID 20886005, 2010). "Furthermore, optimal levels of serum vitamin D have, to date, mainly been determined in terms of parathyroid hormone (PTH) and calcium regulation as well as bone health, but less data is available in relation to the prevention of other diseases such as cancer." (PMID 19649299, 2009). "Elevated PTH may indicate adverse outcomes in certain pediatric cancers." (PMID 39141058, 2024). "The five most significant signaling pathways (adjusted P-value < 0.05) were parathyroid hormone synthesis, secretion and action (bta04928), endocytosis (bta04144), estrogen signaling pathway (bta04915), phospholipase D signaling pathway (bta04072) and choline metabolism in cancer (bta05231)." (PMID 33431058, 2021). "Elevated levels of PTH, BUN, and CRP in our cancer patients suggest an ongoing inflammatory state and altered metabolic balance, conditions previously identified as contributors to increased cancer risk in ESRD populations." (PMID 39712803, 2024). "Parathyroid hormone (PTH)/Pth1r, TGF-β/SMAD, WNT and other signaling pathways are modulated by m6A marks, which are essential in the cellular differentiation and cancer development." (PMID 36527141, 2022). "Serum median PTH, Serum ALP and UCa was significantly higher in the APA and carcinoma groups compared to the classical PA group." (PMID 27901181, 2016). "However, calcium and parathyroid hormone (PTH) levels were only mildly elevated, contrasting with the markedly high levels typically seen in carcinoma." (PMID 42152350, 2026). "PTHrP does not directly regulate the production of PTH by the parathyroid glands, and its actions are more localized, primarily in malignant tumors." (PMID 40062143, 2025). "However, patient 15, classified as having a cancer-type APT, experienced a persistent PTH elevation after a left superior parathyroidectomy." (PMID 40434298, 2025). "High parathyroid hormone (PTH), alkaline phosphatase (ALP), and 24-h urinary calcium excretion levels may be predictive of carcinoma." (PMID 40255501, 2025). "In contrast, another study reported a relationship between PTH and 25OHD in healthy controls, but not in children with cancer." (PMID 38523666, 2024). "PTH and PTHLH share the same PTH/PTHrP receptor but have different roles: PTH primarily regulates the blood calcium level, but PTHLH is involved in many other processes such as chondrocyte growth, mammary gland branching morphogenesis, and cancer." (PMID 36960393, 2023).
cancer (continued). "Significant differences were found in the scope of lymph node dissection, parathyroid resection or not, number of cancer foci, operation method, calcitonin and PTH level between the patients with and without EH (p < 0.05)." (PMID 35722535, 2022). "In rare cases, the culprit cancer produces PTH or both PTH and PTH-rp, while no hyperfunctioning parathyroid gland is present." (PMID 33839893, 2021). "Histological type, cancer volume and thyroid volume did not correlate with post-operative PTH levels." (PMID 34575224, 2021). "Unlike PTH which functions like a peptide hormone, PTHrP does not circulate (except during lactation and cancer)." (PMID 32117726, 2020). "CaSR not only plays a pivotal role in mineral homeostasis by regulating PTH and urinary Ca excretion, but also affects noncalcitropic diseases, such as cancer and cardiovascular disease." (PMID 32517664, 2020). "The mean values of phosphate, calcium, and intact‐parathyroid hormone were controlled to within the target ranges of the clinical guidelines, regardless of cancer status." (PMID 30623084, 2018). "NPPC and PTH have not been previously reported being related to lung cancer, PTH related protein mediated energy wasting in fat tissues, and neutralization of this protein can ameliorate cancer cachexia, which improves patient’s survival." (PMID 33005178, 2020). "However, they demonstrated that reducing sedentary time and increasing physical activity may favor bone formation over resorption in young pediatric cancer survivors via higher levels of bone formation markers (such as ALP) and a positive relation of physical activity with PTH concentrations." (PMID 40725790, 2025). "PTH, GCM2, SYN, CgA, GATA3, and CAM5.2 are always positive in cancer cells, while TTF1, PAX8, CAL, and TG are always negative." (PMID 38019325, 2023).